CCR1 (C-C motif chemokine receptor 1)
Diseases named in the same sentence as CCR1 in open-access papers (continued):
Sharing a sentence is not in itself a finding about the gene and the disease.
multiple myeloma (19 papers, 2011 to 2025). "In other hematological cancers, CX3CR1 and its ligand, CX3CL1, have been proposed to be involved in the interaction between chronic lymphocytic leukemia cells and their microenvironment, and CCR1 has a crucial role in the pathogenesis of myeloma-associated bone disease." (PMID 27258612, 2016). "Even with these challenges, CCR1 antagonists warrant further studies for specific cancers including multiple myeloma." (PMID 35399952, 2022). "In line with this, high levels of CCL3 was found in the bone marrow of patients with multiple myeloma, and anti-CCR1 and anti-CCR5 blocking antibodies inhibit the adherence of myeloma cells to bone marrow stroma cells in vitro." (PMID 32174921, 2020). "Elevated CCL3 in the BM plasma of myeloma further inhibited the erythropoiesis of HSPCs via activation of CCL3/CCR1/p38 signalling and suppressed GATA1 expression." (PMID 33239656, 2020). "Altogether, the data from our study showed that CCL3/CCR1/phos-p38 plays a pivotal role in erythropoiesis of myeloma HSPCs via downregulation of the transcription factor GATA1." (PMID 33239656, 2020). "Real-time PCR and Western blotting further indicated the recovery of GATA1 expression at both the mRNA and protein levels after blocking the CCL3/CCR1/phos-p38 signalling pathway in CD34+ cells from myeloma patients." (PMID 33239656, 2020). "Notably, CCL3 enhances osteoclastogenesis by signalling through CCR1 and CCR5 receptors and has been implicated in the osteolytic activity observed in pathological conditions such as multiple myeloma." (PMID 40471319, 2025). "Antagonists targeting chemokine-receptor 1 (CCR1) may provide a novel approach for treating multiple myeloma." (PMID 35399952, 2022). "This review will discuss whether current CCR1 antagonists are a viable treatment option for multiple myeloma, and studies aimed at identifying which CCR1 antagonist(s) are most appropriate for this disease." (PMID 35399952, 2022). "CCL3 was the main osteoclast-promoting factor in multiple myeloma, which was mediated by CCR1." (PMID 36468006, 2022). "Importantly, blocking the CCL3 signal with BX471 (an antagonist of CCR1) effectively restored the effect of CCL3 on the downregulation of the transcription factor GATA1 in CD34+ cells in the myeloma microenvironment." (PMID 33239656, 2020). "Furthermore, either CCR1 knockout or treatment with a small molecule CCR1 inhibitor strongly inhibits the spontaneous dissemination of human MM cell lines in an intratibial model of myeloma." (PMID 33291672, 2020). "However, reduced expression of cell adhesion molecules like VLA-4, CD44, P-selectin, and CD56, promotion of homing of myeloma cells by decreased expression of chemokine receptors like CCR1, CCR2, and CXCR4, and increased angiogenesis have been proposed as mechanisms." (PMID 31467739, 2019). "The myeloma cells downregulate the surface expression of CXCR4 and instead start expressing another chemokine receptor, i.e., CCR1, which is known to enhance the egress of tumor cells from BM." (PMID 40296907, 2025). "The selective CCR1 antagonist CCX721 has demonstrated efficacy in reducing tumor burden and osteolytic lesions in a murine model of multiple myeloma (MM) by blocking osteoclasts." (PMID 38274805, 2023). "CCR1 and CCR5 are the key players involved in the localization and growth of myeloma cells and in the development of osteolytic lesions." (PMID 33239656, 2020). "These downstream genes mainly include cyclin D2, integrin β7, CCR1, and ARK5, which are responsible for cell cycle progress, bone marrow stromal cell adhesion, MM cell proliferation, and myeloma cell invasion, respectively." (PMID 28673317, 2017). "Specifically, the expression of this chemokine receptor, in addition to CCR1 and CCR2, is correlated with disease state and survival in myeloma patients." (PMID 21375780, 2011).
multiple myeloma (continued). "While multiple CCR1 antagonists have entered the drug pipeline, none have entered clinical trials for treatment of multiple myeloma." (PMID 35399952, 2022). "Therefore, the increased levels of CCR1 and CCR5 expression on HSPCs indicated that myeloma cells adhere to HSPCs and promote myeloma cell localization to and proliferation in bone marrow." (PMID 33239656, 2020). "Moreover, the expression of the CCL3 receptors CCR1 and CCR5 was significantly increased on the surface of HSPCs from myeloma patients." (PMID 33239656, 2020). "The data showed that the levels of CCR1 and CCR5, but not CCR4, were significantly increased on the HSPCs of myeloma patients compared to healthy donors (CCR1: 5.13% ± 1.32% vs. 0.85% ± 0.24%, p = 0.0096; CCR5: 5.72% ± 1.57% vs. 1.91% ± 0.37%, p = 0.0199)." (PMID 33239656, 2020).
multiple sclerosis (17 papers, 2007 to 2025). A progressive autoimmune disorder affecting the central nervous system resulting in demyelination. "Recently, other new CCR1 antagonists have been reported in preclinical studies; for example, J-113863 showed efficacy in animal models of metastatic melanoma, multiple sclerosis and autoimmune encephalomyelitis, while BX471 was tested in models of asthma." (PMID 38750114, 2024). "Some reports have proved that Ccr1 plays an important role in the inflammatory process of a variety of nervous system diseases (Alzheimer’s disease, multiple sclerosis, and cerebral hemorrhage)." (PMID 36875640, 2023). "CCR1 activation contributes to the BBB damage associated with a variety of neuroinflammatory diseases, including multiple sclerosis (MS), diabetes mellitus, and Alzheimer’s disease." (PMID 35062973, 2022). "CCR1 was shown to be upregulated in the CNS following virus infection or certain neurological diseases such as multiple sclerosis." (PMID 32872518, 2020). "Potent CCR1 antagonists have been developed, and several have entered clinical trials, including BX471, which was tested for therapeutic potential in patients with multiple sclerosis." (PMID 40427068, 2025). "Similarly, the CCR1 inhibitor BX471, evaluated as a drug candidate for multiple sclerosis, can alleviate immune infiltration." (PMID 38730482, 2024). "Interestingly, potent antagonists of CCL3 receptors, CCR1 and CCR5, have been developed and their efficacy evaluated in clinical trials against multiple sclerosis among other inflammatory diseases." (PMID 34767551, 2021). "The CC chemokine receptors CCR1, CCR2 and CCR5 are critical for the recruitment of mononuclear phagocytes to the central nervous system (CNS) in multiple sclerosis (MS) and other neuroinflammatory diseases." (PMID 17484785, 2007).
ovarian carcinoma (17 papers, 2001 to 2025). A malignant neoplasm originating from the surface ovarian epithelium. "In ovarian cancer patients, the expression of CCR1 is associated with a poorer prognosis." (PMID 32963283, 2020). "For example, previous studies in our laboratory highlight the role of macrophage-secreted CCL23 promotes the migration and colonization of ovarian cancer cells to the omentum via the CCR1 signaling axis." (PMID 41463176, 2025). "We reviewed reports on CCR1 in multiple cancers, which showed that the higher expression of CCR1 was correlated with a better prognosis of head and neck cancer, ovarian cancer and melanoma." (PMID 38552222, 2024). "CCR1, which is highly expressed in ovarian cancer cells, can mediate ovarian cancer cell‐enhanced migration and metastasis." (PMID 37605299, 2023). "Recently, in a mouse model of ovarian cancer, the small-molecule CCR1 inhibitor UCB35625 demonstrated the ability to reduce cell migration to the greater omentum, a preferential metastatic site for such cancers." (PMID 38274805, 2023). "It has been reported that CCL5-induced invasion of ovarian cancer stem-like cells is mediated by CCR1 and CCR3, and CCR3, along with CCR2 and CCR5, are associated with CCL11-stimulated proliferation, migration, and invasion of ovarian cancer cells." (PMID 34206004, 2021). "Here we report that omental macrophages promote the migration and colonization of ovarian cancer cells to the omentum through the secretion of chemokine ligands that interact with chemokine receptor 1 (CCR1)." (PMID 32963283, 2020). "Targeting of CCR1 in ovarian cancer cells leads to a significant reduction in migration and omental metastasis demonstrating the importance of CCR1 in ovarian cancer cell metastasis." (PMID 32963283, 2020). "CCR1 expression levels in stage I and II ovarian cancer patients showed a significant difference in median progression free survival of 37 months with high CCR1 compared to 96 months with low CCR1 expression (HR 2.13; p = 0.032)." (PMID 32963283, 2020). "We next utilized a small molecule inhibitor of CCR1 (UCB35625) to investigate the therapeutic potential of CCR1 blockade in reducing ovarian cancer migration." (PMID 32963283, 2020). "CCL6 induces the migration of ovarian cancer cells as an important step in colonization via the chemokine receptor CCR1." (PMID 32963283, 2020). "CCR1 is highly expressed in diverse cancers, including prostate cancer cells, ovarian cancer, multiple myeloma, and hematolymphoid neoplasia." (PMID 29212252, 2017). "However, CCL8 in addition to CCL4/5 has been reported to induce the homing of CCR1/5 + intraepithelial CD8 T cells in ovarian cancer, thereby favouring improved response." (PMID 40280979, 2025). "CCL23 is the natural ligand for the cognate receptor, CCR1, which promotes tumor-supportive processes such as the recruitment of myeloid cells, endothelial cell migration, angiogenesis, and T-cell exhaustion in ovarian cancer." (PMID 41463176, 2025). "Accordingly, the other four genes, namely FCGR2B, CD53, CCR1, and SLAMF8, were previously identified as integral components of a larger tumor associated macrophage-related signature with prognostic potential in patients with ovarian cancer." (PMID 37509358, 2023). "Some blockers targeting at CCR1 or CCL23 might improve the clinical outcome of ovarian cancer patients." (PMID 37605299, 2023). "It is reported that omental macrophages promote the migration and colonization of ovarian cancer cells to the omentum through the secretion of chemokine ligands that interact with chemokine receptor 1 (CCR1), and inhibition of CCR1 reduces ovarian cancer colonization." (PMID 36035994, 2022). "We next studied if CCR1 is important in omental colonization by ovarian cancer cells in vivo." (PMID 32963283, 2020).
ovarian carcinoma (continued). "Since CCL6 is expressed primarily by macrophages, we hypothesized that macrophage-derived CCL6 might promote early omental metastasis by interaction with its receptor CCR1 expressed on ovarian cancer cells." (PMID 32963283, 2020). "Furthermore, inactivation of CCR1 in mouse ovarian cancer cells blocks CLL6 induced migration and abolishes their ability to colonize the omentum." (PMID 32963283, 2020). "Taken together, our results redefine the metastatic potential of non-stem cancer cells and provide evidence that targeting the CCL5:CCR1/3/5-NF-κB pathway could be an effective strategy to prevent ovarian cancer metastasis." (PMID 25788271, 2015). "This study suggests that targeting CCR1 or CCL23 in ovarian cancer may be a therapeutic strategy." (PMID 32963283, 2020). "Importantly, inhibition of CCR1 reduced ovarian cancer colonization." (PMID 32963283, 2020). "CCL23 mediated signaling via the CC chemokine receptor 1 (CCR1) promotes TME formation, tumor cell migration, and colonization of ovarian cancer cells to the omentum." (PMID 41463176, 2025). "Based on gene expression data from a cohort of ovarian cancer datasets, including TCGA29, patients with high CCR1 expression had a shortened disease-free survival compared to patients with low CCR1 expressing tumors." (PMID 32963283, 2020). "In CD133+ ovarian carcinoma stem-like cells selected from ovarian carcinoma cell lines and primary tissues, CCL5 and its receptors CCR5, CCR1, and CCR3, were up-regulated." (PMID 32630699, 2020). "Previous studies have demonstrated that CCR1 promotes the invasion of PC3 prostate cancer, hepatocellular carcinoma, ovarian cancer stem-like, and non-small cell lung cancer cells." (PMID 29212252, 2017). "To investigate this, we collected cancer tissues, corresponding metastatic tissues, and paracancerous tissues from 20 patients with epithelial ovarian cancer and determined the expression levels of CCL5 and its receptors (CCR1, CCR3, and CCR5)." (PMID 25788271, 2015). "Thus, CCR1 may be a novel therapeutic target in ovarian cancer." (PMID 11556842, 2001). "In addition to upregulating the expression of CCR1 and CCR5 receptors, macrophages and T cells have been shown to induce ovarian cancer cell death and generate an antitumor immune milieu, according to prior research." (PMID 39030403, 2024). "A role for CCR1 in cancer metastasis has been suggested in other studies, but not in the context of ovarian cancer or mediated by omental macrophage-derived CCL6/CCL23." (PMID 32963283, 2020). "In addition, CCR1 and its ligand CCL5 are highly expressed in ovarian cancer stem-like cells, suggesting the idea of a possible autocrine loop that maintains metastatic capability." (PMID 29212252, 2017). "Because CCR1, CCR10 and CXCR4 are not specific receptors for the proinflammatory chemokines released by ovarian cancer cells, these receptors are likely to interact with chemokines released by other cell types such as immune cells and endothelial cells to the microenvironment." (PMID 23300534, 2012).
melanoma (14 papers, 2013 to 2025). A malignant, usually aggressive tumor composed of atypical, neoplastic melanocytes. "PLP2 binds the ER-resident protein Bap31 and the chemokine receptor CCR1, and decreased PLP2 expression has been implicated in X-linked mental retardation and melanoma metastasis." (PMID 24278019, 2013). "CCR1 inhibitors, therefore, may have therapeutic potential in reducing the progression of melanoma lung metastasis." (PMID 36241867, 2022). "CCR1 expression was identified in fibroblasts and three of the five melanoma cell lines examined." (PMID 26320180, 2015). "It was confirmed in a study on murine models of melanoma, where less metastatic murine melanoma B16F1 cells displayed a lower level of CCR1 transcription as compared to the more aggressive murine melanoma B16F10 cells." (PMID 37185750, 2023). "A considerable difference is also confirmed between CCR1 and CCR2 with regard to the recruited IM subsets, with CCR1 presenting a potential therapeutic target in pulmonary metastasis from melanoma." (PMID 36241867, 2022). "Therefore CCR1, CCR2 and CCR5 presented as candidate targets for preventing pro-tumourigenic IM accumulation in melanoma lung metastasis." (PMID 36241867, 2022). "Moreover, in stage IV melanoma patients with brain metastases, CCL18, CCR1, CCR4, CD274, CSF2, EGF, and PTGS2 genes were significantly over-expressed (p < 0.001, versus patients without melanoma brain metastasis)." (PMID 37091783, 2023).
asthma (13 papers, 2012 to 2025). "mCCL6, hCCL15, and hCCL23 belong to the NC6 subfamily with N-terminal extensions. hCCL23, which binds the cell surface receptor CCR1, has been reported to be associated with total IgE in children with asthma." (PMID 33640900, 2021). "CCR1 and CCR7 are chemokine receptors in Th2/type 2 pathway, which is thought to be the dominant inflammatory pathway underlying severe asthma." (PMID 33602227, 2021). "We then established an OVA-challenged asthma model with conditional CCR1 depletion in the hematopoietic system by total bone marrow transplantion to analyze eosinophil differentiation." (PMID 33640900, 2021). "CCR1 plays a role in the progression of asthma by promoting the chemotaxis of leukocytes in the airway epithelium and probably by modulating the balance of Th1/Th2 cytokine." (PMID 33602227, 2021). "The chemokines CCL3, CCL4, and CCL5 are all associated with the migration of macrophages and other leukocytes through their binding to CCR1, CCR4, and CCR5, and have been linked with asthma." (PMID 31024538, 2019). "Biopsy of the airways has demonstrated elevated expression of CCR1 mRNA in mild-to-severe asthma, and CCR1 expression in ASMC has been revealed by immunohistochemistry." (PMID 23258953, 2012). "Biopsies of airways have demonstrated elevated expression of CCR1 mRNA in mild-to-severe asthma." (PMID 33602227, 2021). "mCCL6 interacts with CCR1, constituting a feedforward loop of asthma exacerbation." (PMID 33640900, 2021). "TNF-α and IFN-γ upregulate CCR1 expression by ASMC, so binding of CCL15 to CCR1 might contribute to the severity and pesistence of asthma." (PMID 23258953, 2012). "In addition, airway smooth muscle cells (ASMCs) have been shown to produce CCL15 in vitro, and these cells express CCR1 in asthma patients." (PMID 23258953, 2012). "Furthermore, TMP has been shown to alleviate lung inflammation in an ovalbumin-induced asthma mouse model by downregulating C-C Motif Chemokine Receptor 1 (CCR1), STAT3, and p38 MAPK proteins, thereby inhibiting airway hyperresponsiveness and the release of inflammatory and chemotactic factors." (PMID 40235541, 2025). "Although the chief role of the CCL15/CCR1 axis has been considered to involve promoting the accumulation of inflammatory cells in the airways of asthma patients; CCL15 may also make a contribution to the severity of asthma and to airflow limitation via effects on ASMC." (PMID 23258953, 2012). "CXCL10 was upregulated in asthma and LCP1, CCR1, PRKCB, IRAK2, LILRA1, and ZEB1 were significantly upregulated in COPD patients." (PMID 36829591, 2023). "Therefore, CCL15/CCR1 signaling could be a target for the treatment of asthma." (PMID 23258953, 2012). "We review the role of CCL15 in the pathogenesis of asthma and also discuss the influence of IgE-mediated immunomodulation via CCL15 and its receptor CCR1." (PMID 23258953, 2012). "These mediators are also important in asthma, but their relation with the CCL15/CCR1 axis remains unknown." (PMID 23258953, 2012). "Although Th17 cells, Th9 cells, and Tregs may be involved in IgE-mediated asthma and seem to have an influence on ASMC, the associations of these Th subsets with the CCL15/CCR1 axis has not been explored in relation to the pathogenesis of asthma." (PMID 23258953, 2012). "However, some trials, like those involving CCR1/AZD4818 for COPD, CCR3/GSK766994 for asthma, and CCL2/Carlumab for IPF, have shown no efficacy." (PMID 39768150, 2024).